FGF2 (fibroblast growth factor 2)
Diseases named in the same sentence as FGF2 in open-access papers (continued):
Sharing a sentence is not in itself a finding about the gene and the disease.
cancer (continued). "The Nanostring cancer progression gene panel revealed a dramatic upregulation of fibroblast growth factor receptor 1 (FGFR1) and its cognate ligand FGF2 in both acquired and inherent resistance." (PMID 27825137, 2016). "FGF2, which often localizes to the nucleus and/or cytoplasm, belongs to the FGF family and regulates the tumorigenesis and progression of a variety of cancers." (PMID 26655091, 2016). "Ongoing clinical trials are recruiting patients with metastatic, advanced, or relapsed/refractory cancers to evaluate the importance of blocking the FGF2/FGFR signaling in progressive and poor outcome cancer patients." (PMID 27007053, 2016). "FGF2/FGFR1 nuclear translocation is vital to activation of PSCs, which is required for cancer progression." (PMID 27061193, 2016). "These biomarkers were the growth factor FGF-2, the angiogenesis factors VEGF and endostatin, and the apoptosis- and cancer cell proliferation-related proteins survivin and Ki67." (PMID 25978323, 2015). "In contrast, most cancer cell lines expressed moderate levels of both HMW and LMW FGF2 isoforms, which appeared cytoplasmic or peri-nuclear." (PMID 24503018, 2014). "Following FGFR blockade, PSCs remaining in the cancer cell layer displayed mainly cytoplasmic staining for both FGFR1 and FGF2." (PMID 24503018, 2014). "In order to assess the relationship between nuclear FGF2 and FGFR1 in stellate and cancer cells, PS1, MIA PaCa-2 and COLO-357 cell lines were subjected to RNAi mediated knock-down of FGF2." (PMID 24503018, 2014). "This cancer trait is elicited by major angiogenesis factors: vascular endothelial growth factor (VEGF), fibroblast growth factor 2 (FGF-2) and platelet-derived growth factors (PDGF)-B and C." (PMID 23325049, 2013). "In contrast, the down-regulation of E-cadherin expression with FGF2 treatment has been observed in tubular epithelial cells and NBT-II carcinoma cells, resulting in increased cell migration and invasion." (PMID 23554977, 2013). "High FGF2 and RHOC levels exhibited a trend towards a correlation with worse patient survival (both overall and cancer-specific)." (PMID 22895562, 2012). "Thus, TGF-β and FGF-2 co-operate with each other to produce ‘activated’ fibroblasts in the tumor microenvironment, and activated fibroblasts may in turn secrete substances such as MMPs to induce invasion and metastasis of adjacent cancer cells." (PMID 22111550, 2012). "The cancer cell induced increase in ECM synthesis by PSCs is thought to be mediated by TGFβ1 and fibroblast growth factor 2 (FGF2), while PSC proliferation is likely mediated by PDGF." (PMID 22973234, 2012). "It was suggested that cancers driven by WNT-1 signaling would likely be enhanced by SULF1, whereas others, where FGF2 or HGF signaling is the more significant driving mechanism, are inhibited." (PMID 23144729, 2012). "Cells were cultured in absence of exogenous growth factors, exposing them to either hypoxia and to neutralizing antibodies targeting growth factors that are frequently deregulated in human cancers, including EGF, FGF-2, IGF-I, PDGF-BB, and VEGF-A." (PMID 23144690, 2012). "Previous studies have demonstrated that cancer cells release proangiogenic proteins, such as VEGF and basic fibroblast growth factor (FGF2)." (PMID 23206527, 2012). "When evaluating all cases collectively, blocking antibodies to FGF-2, HB-EGF, heparanase-1, MT1-MMP, SDF-1 and TGF-β1 significantly diminished carcinoma cell growth stimulation and this effect was antibody dose-dependent." (PMID 23056402, 2012). "Since FGF-2 was shown to protect SCLC cells from cytotoxic drug-induced cell death, we initially sought to extend this observation to the distinct cancer cell type osteosarcoma U2OS cells." (PMID 21625473, 2011). "Divergent functions of growth factors, such as FGF-2 or TGF-beta, in wound healing and cancer have also been reported." (PMID 21042580, 2010).
cancer (continued). "In their capacity as cancer promoters, TAMCs strongly facilitate angiogenesis through the liberation of a number of angiogenic molecules, e.g., TGF-β, EGF, fibroblast growth factor-2 (FGF-2), stem cell factor (SCF), heparin, histamine, MMP-9, and proteases." (PMID 40805183, 2025). "Based on the ceRNA hypothesis, our study identified putative downstream mRNAs regulated by miRNAs, such as FGF2, MCFD2, and PIK3R1, which are often reported to exert oncogenic functions in various cancers, consistent with the findings of most previous studies." (PMID 41141624, 2025). "FGF-2 (also known as bFGF) is the best-characterized member of this group in both normal and cancer settings." (PMID 40872551, 2025). "This suggests that FGF2 and FGFR1 amplification promoted cancer stemness." (PMID 38553760, 2024). "In this study, we compared the impact of FGF2 on cell growth and cancer stemness states in two groups of cancer cells, with and without FGFR1 amplification." (PMID 38553760, 2024). "Indeed, a clear correlation between API5 and FGF-2 expression was observed in an array of cancer cells, and forced expression or siRNA-mediated inhibition of API5 resulted in concomitant FGF-2 expression increase or decrease, respectively." (PMID 38275765, 2024). "Nonetheless, given EMT’s role in carcinoma cell migration, and considering the links that VEGF, FGF-2, and ANG-2 have with EMT, all three angiogenic factors could likely contribute to OSCC metastasizing." (PMID 39120324, 2024). "CAFs could induce angiogenesis, improve the oxygen and nutrient supply, and provide immunosuppressive cytokines to cancer cells, including TGF-β, epidermal growth factor (EGF), platelet-derived growth factor (PDGF), and fibroblast growth factor-2 (FGF-2)." (PMID 36761757, 2023). "Next, we identified significantly enriched KEGG (Pathways in cancer and PI3K/Akt signaling pathway) and GO (GO:0000122, GO:0045944 and GO:0045893) terms, and identified eight genes (EDN1, CCND1, MYB, MYC, RUNX1, ITGA6, IL6 and FGF2." (PMID 36978140, 2023). "To more accurately determine whether circulating FGF2 in ESCC was predominantly produced by cancer cells, we subcutaneously injected KYSE30 or EC9706 cells into nude mice and monitored their FGF2 levels in serum by ELISA assay." (PMID 35941662, 2022). "Moreover, the major cellular component expressing FGF-2 in the NPC microenvironment was epithelial cells, indicating that FGF-2 originated from NPC cancer cells." (PMID 35439170, 2022). "Indeed, the removal of cell surface HS by heparinases potently reduced FGF-2-induced cell proliferation, suggesting the importance of HS6ST2 in augmenting M2 macrophages’ induced cancer cell promotion." (PMID 35954218, 2022). "Cancer cells and other TME cells secretes growth factors like transforming growth factor beta (TGF-β), fibroblast growth factor 2 (FGF2), platelet-derived growth factor (PDGF), and epidermal growth factor (EGF) which are key regulators of fibroblast recruitment and activation." (PMID 36253762, 2022). "TGF-β on these cancer-derived EVs triggered the TGF-β/SMAD3 signalling pathway in recipient fibroblasts and induced myofibroblast-like phenotypes, including the expression of α-SMA and fibroblast growth factor 2 (FGF2)." (PMID 36424598, 2022). "Therefore, FGF-2 and FGF-4, abundant in stromal tissues, enhance EMT of invasive cancer cells, and sustain aggressive phenotypes." (PMID 36140527, 2022). "The action of FGFs, particularly FGF1 and FGF2, has been correlated with chemoresistance in many types of cancer, but the exact mechanisms have not been fully described." (PMID 36276073, 2022).
cancer (continued). "The stemcell niche environment is rich in other growth factors, such as fibroblast growth factor-2 (FGF-2) and epidermal growth factor (EGF), that induce Id expression through the ERK–MEK pathway in cancer cells by direct binding of early growth responsive protein 1 (Egr-1) to the Id promoter." (PMID 34302526, 2022). "Silencing of NRP1 reduced FGF2-dependent ERK activation and inhibited cancer cell growth." (PMID 34830951, 2021). "Cancer cell-derived fibroblast growth factor 2 (FGF2) can facilitate TAM survival and migration through AKT/ERK signaling, activated by neural cell adhesion molecule 1-enhanced classical FGF receptor 1 (FGFR1) and intracellular FGF2/FGFR1 signaling." (PMID 33995371, 2021). "Elevated FGF2 serum levels have been reported in cancer patients compared to healthy individuals, but not exceeding 25 pg/mL, suggesting that the detected levels in PMP tissues are quite high." (PMID 34198773, 2021). "Additionally, through the interaction with various ECM proteins, αvβ3 associates with Vascular Endothelial Growth Factor (VEGF) receptors and Fibroblast Growth Factor-2 (FGF-2), promoting cancer cell invasiveness." (PMID 33916607, 2021). "Indeed, PTTG1 has been shown to transcriptionally activate expression of a wide range of target genes, including c-Myc, FGF-2, cyclin D3, p21, and MMP-2, most of which are critically involved in cancer proliferation and metastasis." (PMID 33250768, 2020). "Additionally, TGF-β is reported to increase fibroblast growth factor-2 (FGF-2) production and mesenchymal stem cell (MSC) differentiation into myofibroblasts to trigger cancer proliferation and invasiveness." (PMID 33396739, 2020). "In light of the observed differences in the pattern of FGF-2 localization, the administration of agents capable of blocking both the paracrine and intracrine activities of FGF-2 in NSCLC cells has been suggested as a potential approach to cancer treatment." (PMID 32230722, 2020). "However, the prognosis of most patients is poor after treatment, and most studies have shown that FGF2 and its receptor (FGFR) are involved in the development of various malignant tumors." (PMID 33381388, 2020). "In addition to metabolic reprogramming providing an energy source to foster cancer cells, TGF-β activated CAFs secrete growth factors, such as TGF-β, FGF2, FGF7, VEGF, PDGF, and HGF, to promote cancer cell proliferation." (PMID 33322749, 2020). "The ability of InsP5 to inhibit Akt activation was not limited to cancer cell lines, as this was also observed in PTEN–/– embryonic stem cells and in human umbilical vein endothelial cells stimulated with basic fibroblast growth factor (FGF-2)." (PMID 33003448, 2020). "Fibroblasts that acquire activated phenotypes in response to the pro-fibrotic factors secreted by cancer cells, such as transforming growth factor-β (TGF-β), platelet-derived growth factor (PDGF), and fibroblast growth factor 2 (FGF2), are termed myoblasts or CAFs19." (PMID 33299639, 2020). "In our study, FGF-2 showed differences in the group of patients with moderately differentiated carcinoma, but not in other groups." (PMID 32963755, 2020). "It actively inhibits FGF2, VEGFA, and ERK1, and promotes the inhibition of cancer development." (PMID 30871059, 2019). "We evaluated the concentration of ANG-2, FGF-2, HGF, IL-8, PDGF-BB, TIMP-1, TIMP-2, TNF-α, and VEGF that are the major cytokines involved in angiogenesis in MM and other cancers and, as previously demonstrated in MM patients, directly correlate with disease activity and increase with progression." (PMID 30626425, 2019).
cancer (continued). "Accordingly, our cell cycle kinetic analyses showed that FGF2 induces a general rather than phase‐specific arrest in Y1K‐Ras‐driven cancer cells." (PMID 30422399, 2019). "Furthermore, nine cancer biomarkers: MIF, TNFα, sFasL, TRAIL, FGF2, SCF, prolactin and OPN, were negatively correlated to Lactobacillus abundance and positively correlated to levels of vaginal pH." (PMID 31089160, 2019). "FGF2 and CHEK4 are up-regulated while the expression of CHEK1, WT1, MDM2, BARD1, BMP2, BAMBI, and SOD2, have been reported to be down-regulated in several cancer subtypes, including CRC." (PMID 31623294, 2019). "We also observed that PROX1 might be in close relation with the pro-angiogenic factor FGF2, which suggests that PROX1 is engaged in the axis of cancer angiogenesis mechanism." (PMID 31717665, 2019). "The secretion of FGF family members by CAFs has been shown in multiple different cancer settings: ovarian CAFs secrete FGF-1, leading to phosphorylation of the receptor, FGFR4; breast CAFs secrete FGF-2 and signal via both FGFR1 and FGFR2; and colon CAFs secrete FGF-1 and -3, and signal via FGFR4." (PMID 31861782, 2019). "It seems that this communication between FGF2 and PROX1 may be a very important mechanism regulating the spreading of cancer cells, which can metastasize via the lymphatic or vascular route depending on the analyzed case." (PMID 31717665, 2019). "Furthermore, ECs can be directly induced by cancer cells through soluble factors (FGF-1, FGF-2, VEGFA, and PDGF-B), activation of adhesion receptor (OPG and JAGGED1), gap junctions (CX43), and vesicles (or exosomes)." (PMID 30662458, 2018). "Taken together, our findings could imply the existence of a co-stimulatory loop whereby FGF-2 produced by cancer cells stimulates secretion of HGF by CAFs which in turn promotes migration and aggressiveness of cancer cells." (PMID 29558956, 2018). "On the other hand, FGF2 from tumour microenvironment also have shown to confer resistance of cancer cells towards imatinib; addition of ponatinib, the multikinase inhibitor of BCR-ABL and FGFR re-sensitized the cancer cells." (PMID 29455663, 2018). "FGF2 is a molecule significantly more stable than FGF1, and binds to FGFR1, FGFR3 and, to a lesser extent, to FGFR2, allowing it to be a targeting molecule for a large group of FGFR-overexpressing cancers." (PMID 30029518, 2018). "In order to set the basis for the development of novel PTX3-derived FGF2 antagonists with potential therapeutic implications, the PTX3-derived pentapeptide ARPCA was characterized in preclinical models of FGF-dependent angiogenesis and cancer." (PMID 30349543, 2018). "In addition, there are many other factors that can stimulate cancer cells to generate ROS, such as insulin-like growth factor I (IGF1), and fibroblast growth factor-2 (FGF2)." (PMID 28282928, 2017). "Cancer cell-derived exosomes containing TGFβ and betaglycan have been reported to induce differentiation of fibroblasts to myofibroblasts by SMAD signaling and upregulation of basic FGF (bFGF, FGF2) production and α-smooth muscle actin expression." (PMID 29112161, 2017). "Ongoing and future clinical trials are warranted to determine whether FGF2 could be incorporated in cancer prognosis and whether FGF targeting therapies have a favorable effect on cancer recurrence and mortality." (PMID 27007053, 2016). "Although FGF2 levels are elevated in several human cancers, FGF2 levels do not always correlate with microvessel density." (PMID 27007053, 2016). "Different expression and localization of FGF2 suggests that FGF2 and different members of FGFR may have different functions and signaling in various cancers." (PMID 27007053, 2016). "More particularly, importin α1 bound directly to FGF1 and FGF2, secreted cNLS-containing growth factors, and addition of exogenous importin α1 enhanced the activation of ERK1/2, downstream targets of FGF1 signalling, in FGF1-stimulated cancer cells." (PMID 26887791, 2016).
cancer (continued). "In addition, FGF2/FGFR inhibitors are being developed and evaluated as monotherapy or as part of a combination therapy for the treatment of different types of cancer." (PMID 27007053, 2016). "Over the years the FGF2/FGF receptor (FGFR) system has been shown to play a major role in angiogenesis, inflammation and in the development and progression of angiogenic diseases and cancer." (PMID 25609197, 2015). "While cancer cells adhered to immobilized FGF-2 this adhesion was not integrin dependent (data not shown)." (PMID 25973543, 2015). "Previous studies have reported that tumors may acquire resistance to anti-VEGF therapy following angiogenesis reactivation, which is induced by compensatory upregulation of FGF2/FGFR system in experimental animals and patients with cancer." (PMID 26694358, 2015). "Exogenous soluble FGF-2 did not induce cancer cell elongation and FGF-2 protein was readily detected by Western blotting in fibroblast but not in cancer cell lysates." (PMID 25973543, 2015). "In vitro, inhibiting FGFR1 and FGF2 in PSCs, using RNAi or chemical inhibition, resulted in significantly reduced cell proliferation, which was not seen in cancer cells." (PMID 24503018, 2014). "Platelet-derived growth factor (PDGF), fibroblast growth factor 2 (FGF2) and TGF-β released by cancer cells may be candidates to mediate fibroblasts activation, but the previous data were not sufficient to support this notion." (PMID 21249190, 2011). "Even though deletions in chromosome 4 is a common feature in CRC, and known cancer genes such as KIT, EGF and FGF2 are situated here, none has yet been verified as predisposing for early onset or hereditary CRC." (PMID 20459617, 2010). "Interestingly, for six genes (KISS1, CXCR4, PSMB9, ABCB1, FGF2, and IL6) found to be up-regulated along with GCS, their overexpression pursuant to platinum-agent treatments in patients promoted resistance to those same agents in cancers." (PMID 40507922, 2025). "Due to the inability to obtain all of the necessary clinical data on samples from children with ALL, we compared the results of the quantitative analysis of VEGF-A and FGF-2 only with the concentrations of the same biomarkers in the serum of children without diagnosed cancer or inflammatory lesions." (PMID 38473833, 2024). "Further analysis using a human cancer stem cell qPCR array revealed that, relative to tnLCM or control, exposure of TNBC cells to tbLCM leads to downregulation of the transcription factor and putative tumor suppressor Dachshund homolog 1 (DACH1), a downstream regulator of FGF2." (PMID 38581619, 2024). "Moreover, direct (through gap junction and calcium signaling) and indirect (through fibroblast growth factor 2 (FGF2) and platelet-derived growth factor-DD (PDGF-DD) secretion) interactions between cancer cells and osteogenic cells leads to a reduction in estrogen receptors." (PMID 37182144, 2023). "As the FGF2 rs1048201, PDGFRB rs246395, PDGFRA rs2228230, MMP2 rs243865, rs7201, and TIMP2 rs7501477 have not been previously examined in HNSCC in terms of survival and treatment outcome, this is most likely the first report describing their prognostic and predictive value in this type of cancer." (PMID 35406617, 2022). "FGF2 does not yet have any approved drugs used in cancer treatment." (PMID 35456223, 2022). "In non-cancer models, effects on macrophages by FGF2 have not been directly described." (PMID 32792542, 2020). "In addition, increased FGF-2 levels have been found in several human cancers, but FGF-2 levels do not always correlate with microvessel density." (PMID 32456056, 2020).